ZEB1 (zinc finger E-box binding homeobox 1)
Diseases named in the same sentence as ZEB1 in open-access papers (continued):
Sharing a sentence is not in itself a finding about the gene and the disease.
tumor (1,454 papers, 2009 to 2026). "One notable EMT-related protein is zinc finger E-box–binding homeobox 1 (ZEB1), implicated in tumor progression." (PMID 41216500, 2026). "Our results suggest that EMT-TFs, particularly the interplay between SNAI1 and ZEB1 is associated with tumor progression, metastasis, and poor survival." (PMID 41481650, 2026). "The EMT is considered a cellular process to induce cell stemness, which causes tumor metastasis and treatment resistance, for instance, ZEB1, SNAI1, and TWIST1." (PMID 39827156, 2025). "These biophysical properties were correlated with ZEB1 mRNA expression, revealing preliminary associations between tissue relaxation behavior and molecular signatures relevant to tumor microenvironment dynamics." (PMID 40856386, 2025). "To determine the impact of ZEB1 loss in macrophages on tumor growth, we first employed a syngeneic subcutaneous (s.c.)model of CRC by injecting CMT-93 cells into LysMCtrl and LysMΔZeb1 mice." (PMID 40595293, 2025). "Among these, 17 genes were strongly associated with LC, whereas ERBB2, SP1, and ZEB1 were related to other tumor types." (PMID 41226027, 2025). "ZEB1 regulates tumor-associated macrophage migration in hypoxic cancer and is a key factor in maintaining tumor-associated macrophages and promote caner progression." (PMID 40016707, 2025). "As phagocytosis of fluorescent bioparticles and tumor cell debris was insignificantly - withal minimally – altered in Zeb1-deficient compared to -proficient BMDMs, we screened for secreted cytokines." (PMID 40595293, 2025). "Consistently, co-culture of BMDMs with tumor cells increased tumor cell proliferation and invasion, yet to the same extent in ZEB1-proficient and -deficient BMDMs." (PMID 40595293, 2025). "Specifically, in cancer-associated fibroblasts (CAFs), ZEB1 was described to be crucial for fibroblast plasticity regulating immune infiltration and supporting tumor progression." (PMID 40595293, 2025). "This study examined 50 PTC cases, revealing significant associations between E-cadherin and zinc finger E-box-binding homeobox 1 expression and lymph node metastasis, clinical stage, and tumor grade." (PMID 40787244, 2025). "The mesenchymal markers SNAIL, SLUG, TWIST, and ZEB1 were upregulated in OX40+ tumor ECs, whereas the adhesion molecules CDH1 (encoding E-cadherin) and CDH5 (encoding VE-cadherin) were downregulated." (PMID 40026246, 2025). "ZEB1 and IL-17 exhibit a close association and forming a feedback loop in tumor invasion, immune regulation, and inflammatory diseases." (PMID 40016707, 2025). "In vivo, ablation of the Zeb1 allele in the PDAC KPC mouse models showed decreased tumour progression and metastasis, while re-expression of Zeb1 led to progression and invasive stages." (PMID 38978141, 2024). "Although our previous study reported that ZEB1 facilitates tumour-associated macrophage (TAM) infiltration, its roles in hypoxia-induced immune evasion need to be further investigated." (PMID 38183060, 2024). "Intrinsically high Zeb1 expression characterizes many types of undifferentiated carcinomas and studies demonstrated the association of such tumours with high abundance of PUFA-containing phospholipids and respective enzymes." (PMID 39009641, 2024). "Among these four gene, Zinc finger E-box binding homeobox 1 (ZEB1) is a key factor associated with tumor migration and invasion." (PMID 38693503, 2024). "High expression of the zinc finger protein ZEB1 promotes the differentiation of tumor-associated macrophages into cancer-promoting macrophages (M2) by upregulating CD74 expression in tumor cells, thus inducing immune escape and leading to poor prognosis." (PMID 39118044, 2024). "In tumor stem cells, ZEB1/2 expression in epithelial cells causes EMT and mesenchymal phenotypes with invasiveness, metastatic, and dedifferentiation potential." (PMID 38543112, 2024).
tumor (continued). "As Zeb1 mechanistically links the mesenchymal state-associated tumour-promoting effects with high ferroptosis sensitivity, our data indicate a therapeutic vulnerability of these highly plastic, pro-metastatic and therapy-resistant cancer cells." (PMID 39009641, 2024). "Further studies have reported that HIF1A overexpression enhances ZEB1 trans-activity by binding to its promoter leading to a loss in E-cadherin causing increased invasion, migration and tumor progression." (PMID 38877052, 2024). "As illustrated in the MM10 tumor, which bore the presence of a well-defined ZEB1high clone, increased ZEB1 expression was not only associated with low ZEB2 and MITF expression, but also with decreased SOX10 levels." (PMID 38519642, 2024). "Collectively, our data indicate that ZEB1 limits the sensitivity of fibroblasts to NFκB-activating signals, which causes an iCAF bias affecting tumor immune infiltration." (PMID 38937629, 2024). "To inspect the clinical implications of cell communications between CAFs, macrophages, endothelial cells, and tumour cells, we detected expression associations between signature genes (FGF7/THBS1/MS4A4A/ZEB1) and tumour miRNAs." (PMID 38778448, 2024). "Consistent with increased M-CSF expression, Esc and Zeb1/Snail OE tumors exhibited an increased abundance of tumor-associated macrophages (TAMs)." (PMID 38378697, 2024). "ZEB1 has been implicated in carcinogenesis in breast tissue because it enhances tumor cell migration and invasion." (PMID 36899736, 2023). "Due to their target genes were mainly focused on EMT, miR-200 family are associated with tumor metastasis, for instance, zinc-finger E-box-binding homeobox 1 (ZEB1) and transforming growth factor β1 (TGFβ1)." (PMID 37333450, 2023). "USP43 can enhance CRC cell growth by inducing the deubiquitination of Zinc finger E-box-binding homeobox 1 (ZEB1) protein, which is closely associated with tumor cell proliferation, invasion, migration and expression of EMT-related biomarkers." (PMID 37251574, 2023). "It was reported that hypoxia-induced ZEB1 promoted cervical cancer progression via CCL8-dependent tumor-associated macrophage recruitment." (PMID 36644609, 2023). "It has been demonstrated that increased ZEB1.AS1 expression is linked to tumor development and metastasis." (PMID 37868992, 2023). "Izmuchenko reported that the miR-200 family regulating the expression of factors implicated in tumor metastasis, e.g., E-cadherin and ZEB1, is significantly downregulated in the triple-negative breast cancer cells undergoing EMT in response to TGF-β." (PMID 37460910, 2023). "By contrast, comparable ZEB2 expression levels were observed in the M13HS-2 and -8 tumor hybrids and their ZEB1-KO variants." (PMID 38139138, 2023). "The expression of Zeb1 was positively associated with glycolytic dysregulation and the accumulation of M2-like tumor-associated macrophages (TAMs)." (PMID 37881499, 2023). "Consistently, in the xenograft tumor model, ZEB1 knockdown significantly neutralized DIO3OS deficiency‐induced tumor growth." (PMID 37271897, 2023). "Thereby, high ZEB2 and low ZEB1 expression levels were associated with primary tumor growth, differentiation, metastatic outgrowth and survival." (PMID 38139138, 2023). "The positive expression of UBE2C and ZEB1 were positively associated with tumor stages, local lymph node metastasis, and International Federation of Gynecology and Obstetrics (FIGO) stages." (PMID 37335710, 2023). "A partial downregulation of Zeb1 in several cell types (e.g., cancer cells, tumor-associated macrophages, myofibers, adult muscle stem cells) is sufficient to block its homeostatic functions." (PMID 38097578, 2023). "ZEB1 is a multifunction and vital gene encoding the zinc finger E-box binding homeobox 1 protein, involved in many embryonic development processes and tumor progression/metastasis through epithelial–mesenchymal transition (EMT)." (PMID 36204226, 2022).
tumor (continued). "We also noticed increased expression of the EMT activator ZEB1, the tumor-associated antigens MAGEA3/A6 and MAGEC2, and metalloproteinase in EMThi cancer cells." (PMID 35503263, 2022). "ZEB1 is expressed in the tumor invasive zone of human GBM tissues, which is associated with hypoxic regions of the tumor." (PMID 36402997, 2022). "Zinc Finger E-Box Binding Homeobox 1 (ZEB1) as a transcription factor was associated with poor prognosis in ICC and ZEB1 expression in ICC cells induced tumor EMT and stemness phenotype." (PMID 35971182, 2022). "The results of GSEA demonstrated that the loss of Zeb1 expression in PyMT;Zeb1cKO tumor cells led to downregulation of genes associated with the glycolysis signature compared with the enrichment observed in PyMT tumor cells." (PMID 35246504, 2022). "Some TFs are associated with multiple PTPs, such as several tumor metastasis regulators (ZEB1, SNAI3, and SMAD2)." (PMID 36341348, 2022). "To clarify the molecular mechanism of ZEB1 and CP, we divided the 471 tumor patients in TCGA into high- and low-risk groups." (PMID 35232428, 2022). "SREBP-1 and ZEB1 are potential targets of miRNA-142-5p, a tumor suppressor, and they are associated with tumor progression and poor prognosis." (PMID 35912181, 2022). "In these tumours, ZEB1 expression correlates with the loss of E-cadherin and is associated with advanced disease or metastasis, indicating the relevance of ZEB1 induction of EMT and tumour progression." (PMID 36499447, 2022). "Consistently, spontaneous lung tumors in mice with inactivated Zeb1 harbor a significantly reduced PD-L1 expression at the invasive front, associated with a stronger anti-tumor immunity in this model." (PMID 35432344, 2022). "ZEB1 modulates the polarization of M2-polarized tumor-associated macrophages (TAMs) via EMT regulation." (PMID 36402997, 2022). "BCL6 also has a positive effect on the induction of EMT associated with the increase of ZEB1, leading to the suppression of E-cadherin and consequently tumor progression." (PMID 36402997, 2022). "The experiment found that lowering ZEB1 causes pancreatic cell lines to lose the ability to form tumor spheres in vitro, and tumor initiation in vivo, hence confirming the requirement of stemness for Zeb1." (PMID 36076302, 2022). "miR-203 silencing by ZEB1 is strongly associated with tumor recurrence after treatment with gemcitabine." (PMID 33803458, 2021). "EMT and immunosuppression of CD8+ tumor-infiltrating lymphocytes, which are important factors of cancer progression, are linked via miR-200 and ZEB1 transcription factor." (PMID 34660694, 2021). "One area where there is some discrepancy between the 2 studies is that Almotiri and colleagues suggest that Zeb1 plays a tumor suppressor role in AML progression whose loss enhances AML lethality." (PMID 34550965, 2021). "First, we did not use NSCLC cell lines with EGFR L858R mutation, although we showed that ZEB1 was highly expressed in tumor specimens from NSCLC patients with EGFR L858R mutation after gefitinib resistance." (PMID 33764690, 2021). "ZEB1 also can activate signaling pathways associated with tumor metastasis, including PI3K/AKT and WNT5a." (PMID 34916487, 2021). "A previous study showed that the loss of Zeb1 in the cancer cells of KPC mice leads to decreased metastasis associated with a trend toward decreased primary tumor growth, and an insignificant difference in disease-free survival of the mice." (PMID 33852841, 2021). "Notch/ZEB1 signalling has recently been implicated in the critical interaction between BCSCs and the tumour microenvironment." (PMID 34295896, 2021). "Meta-program B contained GNP-associated genes such as Math1 and Zeb1, likely corresponding to undifferentiated progenitors in each tumor." (PMID 34210306, 2021).
tumor (continued). "Inaddition, it has been shown that ZEB1 knockdown in the same transgenicin vivo model is associated with a loss of cell plasticity(fixation of the epithelial phenotype by tumor cells), as well as a reductionin the invasive and metastatic abilities." (PMID 33173593, 2020). "Higher levels of ZEB1 are associated with aggressive cancer features, high tumor grade, resistance to therapy, metabolic plasticity, increased incidence of metastasis, and worse clinical prognosis in the vast majority of human cancers." (PMID 32570918, 2020). "Loss of Zeb1 expression in PyMT;Zeb1cKO tumor cells was confirmed by immunohistochemical staining and immunoblotting." (PMID 33046710, 2020). "This enhanced the anti-tumor immune response while regulating EMT through ZEB1, inhibiting tumor growth and metastasis, and ultimately causing tumor regression." (PMID 32536914, 2020). "In NSCLC the activation of EMT by the up-regulation of ZEB1 transcriptional factors causes the up-regulation of PD-L1 by tumor cells, leading to CD8+ T cells immune suppression and increased metastasis." (PMID 33123122, 2020). "In colorectal cancer (CRC) cells, it was found that tumor suppressor death domain-associated protein (DAXX) is able to prevent ZEB1 modulation on E-cadherin to inhibit the invasion and proliferation of tumor cells." (PMID 32664703, 2020). "ZEB1 expression was significantly associated with vascular invasion, tumour stage, and presence of satellite lesions." (PMID 31543517, 2019). "Further, RUNX1, ZEB1 or TWIST1 expression didn’t show association with clinicopathological features in any of the analyzed tumor types." (PMID 31655611, 2019). "ZEB1 plays important roles in malignant lymphocytes and in tumor-associated macrophages, but its expression and role in immune cells in the context of tissue damage and repair has not been studied." (PMID 30910999, 2019). "When samples were split by median stroma-adjusted ZEB1 expression, ZEB1 was significantly associated with a lower percentage of monocytes (p = 0.026) and lymphocytes (p = 0.004) in primary tumor samples." (PMID 31780722, 2019). "In particular, the expression of PRMT1 and ZEB1 in ccRCC, as well as low-nuclear tumor grade and low-tumor stage were significantly associated with better cancer-specific survival (p = 0.029, p = 0.009, p < 0.001 and p < 0.001, respectively)." (PMID 31655611, 2019). "Transcriptomic analyses across various carcinomas proposed association of ZEB1 mRNA expression and tumor aggressiveness, including metastatic potential." (PMID 29744893, 2018). "ZEB1 has been implicated in neoplastic transformation, tumor progression, and metastasis in several different tissue types including lung, breast, and colon cancer." (PMID 32309604, 2018). "These three mesenchymal transition factors expressions have been linked to the tumor resistance to treatment: for example, ZEB1 promotes the resistance against temozolomide (TMZ), the standard-of-care chemotherapeutic today." (PMID 30167084, 2018). "While some of the molecular mechanisms that control levels of both of the ZEB proteins have been documented, there are now new tumour suppressor candidates implicated in the control of ZEB1 and ZEB2." (PMID 29963231, 2018). "We observed a significant association between the ZEB1 level and the grade of differentiation shown by the original primary tumor (P = 0.020, concordance rate 75%)." (PMID 28700115, 2017). "Immunofluorescence and immunohistochemistry studies using human clinical samples showed that ZEB1 is expressed along the tumor invasive front, in pseudopalisades, which are associated with hypoxic areas of the GBM." (PMID 29165393, 2017).
tumor (continued). "Some of these collectively invading cohorts – referred as ‘tumor buds’ – displayed loss of cell polarity, reduced total levels and membrane localization of E‐cadherin, and increased nuclear ZEB1." (PMID 28548345, 2017). "The study proved that down-regulation of miR-150 contributed to malignant potential in ESCC through targeting EMT inducer, ZEB1 and was also associated with poor prognosis and tumour progression." (PMID 28931826, 2017). "ZEB1 overexpression is associated with tumor cells migration and invasion and together with inhibition of E-cadherin gene expression mediates progression to metastasis." (PMID 29206234, 2017). "Since increased ZEB1 expression by tumor cells has been associated with hypoxia and invasion, we analyzed regional ZEB1 expression when approaching the tumor edge or in perinecrotic areas." (PMID 28945795, 2017). "Tumor-derived cells elicited an epithelial-mesenchymal transition associated with upregulation of Zeb1 and Twist1/2 and enhanced tumor initiating and invasive capacities." (PMID 28740236, 2017). "Given the deleterious effects of ZEB1 loss on patient survival, we wanted to determine if loss of ZEB1 was associated with increased stemness as the basis and link to both tumor virulence and poor patient survival." (PMID 28246407, 2017). "This percentage was higher than that of tumours with lower ZEB1 (9 KRAS-mutated tumours in a total of 31 tumours; 29%), but the association between KRAS mutations and ZEB1 expression changes was not statistically significant (Fisher's exact test, P=0.11)." (PMID 27456471, 2016). "Epithelial-mesenchymal transition (EMT) is a pathological event largely associated with tumour metastasis with studies demonstrating Wnt-signalling through Snail1 and Zeb1 regulates bone metastasis in lung cancer." (PMID 27590724, 2016). "We found that the changes in gene expression in tumours versus normal tissues were similar to what we observed in the Oncomine data sets, namely that tumours had an epithelial-like CDH1high/VIMlow phenotype, which was associated with lower ZEB1 expression." (PMID 27456471, 2016). "ZEB1 expression is associated with aggressive behaviour in many tumour types, but the potent effects cannot be solely explained by its proven function as a transcriptional repressor of epithelial genes." (PMID 26876920, 2016). "Consistently, ZEB1 also promoted KRAS-mutated xenograft tumour growth but suppressed EGFR-mutated xenograft tumour growth." (PMID 27456471, 2016). "The loss of p63 results in the downregulation of tumor suppressive miR-205, causing upregulation of ZEB1 and ZEB2, which in turn, suppresses E-cadherin." (PMID 27588490, 2016). "By inhibiting E-cadherin expression, ZEB1 was found to cause intercellular adhesion damage and weaken links with the basement membrane, resulting in invasion and metastasis of tumor cells from the primary place." (PMID 27861158, 2016). "In five of six data sets containing ZEB1 expression data, tumours had lower ZEB1, which was associated with the epithelial-like phenotype of the tumours and supported the role of ZEB1 as a driver of EMT." (PMID 27456471, 2016). "In total, 28/62 (45.2%) of SS genomes showed evidence of loss-of-function alterations of ZEB1 strongly implicating this gene as a tumour suppressor involved in the pathogenesis of SS." (PMID 26415585, 2015). "The clinical samples further revealed that miR-652 was decreased in PC tissues and antagonistically correlated with ZEB1 expression, associating with late tumor stage, lymphatic invasion and metastasis." (PMID 26498682, 2015). "Positive expression of ZEB-1 in 23 HCCs (21.3%) was significantly associated with vascular invasion (p = 0.016) and advanced tumor TNM stage (p = 0.023)." (PMID 24304617, 2013). "We found that these events occurred in tumor-bearing iron deficient mice, as mRNA levels of Snai1, 2 and Zeb1, 2 were upregulated at least one-fold in the primary tumors of mice fed an iron deficient diet." (PMID 23800380, 2013).